SMYD3 (SET and MYND domain containing 3)
Description:
Histone methyltransferase. Specifically methylates 'Lys-4' of histone H3, inducing di- and tri-methylation, but not monomethylation. Also methylates 'Lys-5' of histone H4. Plays an important role in transcriptional activation as a member of an RNA polymerase complex. Binds DNA containing 5'-CCCTCC-3' or 5'-GAGGGG-3' sequences.
Synonyms: ZMYND1; ZNFN3A1; KMT3E; bA74P14.1
Tractability: Small molecule: a structure with a bound ligand is known; a high-quality ligand is known; it has a high-quality binding pocket. PROTAC: ubiquitination databases record sites on it; its protein half-life has been measured; a small molecule that binds it is known.
Target class: Writer; Protein methyltransferase; SET domain; Epigenetic regulator
Chemical probes: BAY-6035 (high quality)
Gene: Protein-coding gene on chromosome 1 (245,749,342 to 246,507,312, reverse strand). Ensembl gene ENSG00000185420.
Subcellular location: Cytoplasm; Nucleus
Subcellular location (Human Protein Atlas): Nucleoplasm; Cytosol
Pathways (Reactome):
Chromatin organization: PKMTs methylate histone lysines
Gene Ontology:
Molecular function: histone H4 methyltransferase activity; protein binding; histone H3K36 dimethyltransferase activity; histone H3K4 trimethyltransferase activity; histone methyltransferase activity; RNA polymerase II cis-regulatory region sequence-specific DNA binding; RNA polymerase II complex binding; RNA polymerase II intronic transcription regulatory region sequence-specific DNA binding
Biological process: heart development; negative regulation of DNA-templated transcription; chromatin remodeling
Cellular component: nucleus; nucleoplasm; cytoplasm
Genetic constraint (gnomAD): Loss-of-function variants: 30 observed, 45.32 expected, observed/expected ratio (o/e) 0.66, 90% interval 0.49 to 0.9. The upper end of that interval is the gene's LOEUF score, 0.9, which puts it in group 3 of 6, group 1 being the genes least tolerant of losing a copy. Missense variants: 447 observed, 476.19 expected, observed/expected ratio (o/e) 0.94, 90% interval 0.87 to 1.01. Synonymous variants: 184 observed, 168.16 expected, observed/expected ratio (o/e) 1.09, 90% interval 0.97 to 1.24.
Homologues: Orthologues: chimpanzee SMYD3 (99% identical), macaque SMYD3 (99% identical), rabbit SMYD3 (96% identical), guinea pig SMYD3 (95% identical), pig SMYD3 (95% identical), rat Smyd3 (95% identical), mouse Smyd3 (94% identical), dog SMYD3 (93% identical), tropical clawed frog SMYD3 (53% identical), zebrafish smyd3 (46% identical), Drosophila melanogaster Smyd3 (28% identical), Drosophila melanogaster SmydA-5 (22% identical), and 7 more. Paralogues in human: SMYD2 (32% identical), SMYD1 (30% identical), SMYD4 (24% identical), SMYD5 (20% identical), ZMYND15 (15% identical).
Diseases named in the same sentence as SMYD3 in open-access papers:
SMYD3 is named in the same sentence as 102 diseases in open-access papers, as found by Europe PMC text mining. Sharing a sentence is not in itself a finding about the gene and the disease. The quoted sentences say what the papers report.
breast carcinoma (58 papers, 2010 to 2025). "Chromatin immunoprecipitation assays performed in breast cancer cells have shown direct association of the histone methyltransferase SMYD3 with the SHCBP1 promoter, facilitating transcriptional induction through H3K4me3 modification." (PMID 41009347, 2025). "As demonstrated in earlier studies, higher SMYD3 expression was associated with a worse prognosis in several types of cancer, including hepatocellular carcinoma and claudin-low breast cancer." (PMID 37386026, 2023). "SMYD2 and SMYD3 are upregulated in 10% of patients with breast cancer and are significantly associated with cancer progression and poor prognosis in luminal breast cancer." (PMID 35453496, 2022). "SMYD3 is associated with cancer cell proliferation and was reported to be overexpressed in hepatocellular, colorectal, prostate, and breast carcinomas." (PMID 35884603, 2022). "SMYD3 is upregulated in various types of tumors, including colorectal, lung and breast cancer, and is associated with a poor prognosis." (PMID 36057625, 2022). "The SMYD3 VNTRs have been shown to be a susceptibility factor for human cancers, especially for colorectal cancer, breast cancer and HCC20." (PMID 32071406, 2020). "E2F-1 was shown to be involved in the transcriptional activation of the SMYD3 gene, and a variable number of tandem repeat polymorphisms of an E2F-1 binding element in the SMYD3 promoter region was considered as a risk factor for familial breast cancers." (PMID 32007952, 2020). "The present study aims to explore the correlations of EZH2 and SMYD3 gene polymorphisms with breast cancer susceptibility and prognosis." (PMID 29089464, 2018). "A variable number of tandem repeats (VNTRs) polymorphism in the SMYD3 promoter region is a risk factor for familial breast cancer and esophageal squamous cell carcinoma." (PMID 29089464, 2018). "The aim of the present study was to investigate the correlation of enhancer of Zeste homolog 2 (EZH2) and SET and MYND domain containing 3 (SMYD3) gene polymorphisms with breast cancer susceptibility and prognosis." (PMID 29089464, 2018). "Only recently SMYD3 has been linked to H2A.Z: In breast cancer cells, dimethylation of H2A.Z at K101 by SMYD3 promotes cell proliferation at least in part by activating cyclinA1 expression." (PMID 29495465, 2018). "In addition to its association with tumorigenesis, SMYD3 has also been reported to methylate histone H2A.Z.1 at lysine 101 in the promoter of cyclin A1, promoting cyclin A1 transcription in breast cancer." (PMID 38191478, 2024). "In summary, SMYD3 is overexpressed and associated with poor prognostic outcomes in breast cancer." (PMID 33637115, 2021). "Our study found that C allele of EZH2 rs12670401, T allele of EZH2 rs6464926, and 3 allele of SMYD3 VNTR could increase the susceptibility to breast cancer." (PMID 29089464, 2018). "Indeed, SMYD3 has been strongly implicated as a proto-oncogene in hepatocellular, colorectal and breast carcinomas by virtue of its high over-expression and promoter-associated polymorphisms specific to malignant cells." (PMID 25738358, 2015). "SMYD3, a protein with histone methylation function that could accelerate the methylation of chromosomes histone, is associated with the transcriptional cell regulation and presents high expression in a variety of tumors (breast cancer included)." (PMID 29089464, 2018). "Thus, we hypothesized that SMYD3 gene polymorphisms may be involved in the development and progression of breast cancer through combining with other genes and environmental factors." (PMID 29089464, 2018). "Of note, our analysis of cBioportal data revealed SMYD3 amplification in up to 24% of breast cancers." (PMID 40157910, 2025). "Brca1 deficiency together with ERα signaling enhances SMYD3-SHCBP1 expression, leading to more profound mammary tumor formation in parous mice than virgin mice." (PMID 40157910, 2025).
breast carcinoma (continued). "In this study, we showed that BRCA1 deficiency together with ERα signaling enhances SMYD3-SHCBP1 expression, which activates their downstream signaling, leading to the formation of mammary tumors in mice." (PMID 40157910, 2025). "Consistently, combined inhibition of SMYD3 and PARP, which is one of the most studied DDR targets, emerged as a promising synthetic lethality strategy in HR-proficient gastrointestinal and breast cancers expressing high levels of SMYD3." (PMID 38812026, 2024). "Using data retrieved from TCGA, we analyzed the expression of SMYD3 in normal breast and various breast cancer subtypes." (PMID 38322121, 2024). "Results showed that the expression of SMYD3 is particularly low in basal-like breast cancer compared to other subtypes." (PMID 38322121, 2024). "Accordingly, we explored the relationship between the expression of HOXB2 and SMYD3 in breast cancer cell lines using data retrieved from CCLE dataset, and found a positive correlation." (PMID 38322121, 2024). "Our studies confirmed that ZNF8, which interacts with Smad3, plays a critical role in the regulation of breast cancer metastasis via TGF‐β through SMYD3." (PMID 39225541, 2024). "In breast cancer, SMYD3 expression is significantly upregulated and correlated with shorter patient survival." (PMID 39482529, 2024). "In this study, through extensive molecular characterization of gastrointestinal and breast cancer cells, we found that SMYD3 is part of a multiprotein complex that is involved in DNA damage response and also comprises AMPK and mTOR." (PMID 37998381, 2023). "To this end, we used HCT-116 colorectal cancer, AGS gastric cancer, and MDA-MB-231 breast cancer cells, in which we previously showed that SMYD3 is required for DNA repair upon NCS exposure." (PMID 37998381, 2023). "SMYD3 is overexpressed in hepatocellular carcinomas and colorectal carcinomas and contributes to the proliferation of breast carcinoma cells." (PMID 36838987, 2023). "SMYD3 is overexpressed in cancers, including breast cancer, colon cancer, prostate cancer, lung cancer, and pancreatic cancer, where it correlates with poor prognosis." (PMID 36838987, 2023). "In this work, we examined the structural features of SMYD3 that interact favorably with Inhibitor-4, and also assessed its effects on colorectal and lung cancer cell lines, which, along with breast cancer lines, have been shown to overexpress SMYD3." (PMID 35076487, 2021). "We recently developed a panel of SMYD3 inhibitors, one of which (Inhibitor-4) effectively restricted the proliferation of breast cancer cells." (PMID 35076487, 2021). "Many studies have demonstrated that SMYD3 acts as an oncogene in hepatocellular carcinoma, breast cancer, ovarian cancer, and renal cell carcinoma, in which SMYD3 regulates downstream targets involved in proliferation and metastasis." (PMID 33708629, 2021). "Future studies of both NO and NO combinations with SMYD-3 inhibition on breast cancers are necessary to determine their efficacy in clinical applications, such as 3D cell culture platforms and animal models." (PMID 34842655, 2021). "A previous study on breast cancer reported that excessive expression of SMYD3 increased cell tolerance to cisplatin treatment in MCF-7 cells." (PMID 34201935, 2021). "Ultimately, these results highlight the Group 2 combination therapeutic, NO (from GSNO) + SMYD-3 inhibition (from inhibitor-4) as an extremely promising treatment for continued application in breast carcinoma treatment." (PMID 34842655, 2021). "Herein, the novel combination of NO, delivered via S-Nitrosoglutathione (GSNO), and SMYD3 inhibition, with inhibitor-4, is investigated for anticancer potential against breast cancers." (PMID 34842655, 2021). "We previously developed a small molecule SMYD3 inhibitor using a random screen in silico, and demonstrated its efficacy in limiting the growth and survival of breast cancer cells (Inibitor-4,)." (PMID 35076487, 2021).
breast carcinoma (continued). "It was also noted that SMYD3 transcripts appear to be elevated in all breast cancer subtypes, further demonstrating the importance of SMYD3 in breast cancer." (PMID 33637115, 2021). "In breast cancer (BC) cells, SMYD3 can regulate the cell cycle and promote cancer cell migration by combining with the cyclin A1 (CCNA1) and myosin light chain 9 (MYL9) promoters." (PMID 34335697, 2021). "Western blot and immunocytochemistry were carried out to test the expression levels of SMYD3 using anti-SMYD3 antibody in normal and breast cancer cell lines." (PMID 33333978, 2020). "Western blot data have indicated that SMYD3 was highly expressed in breast cancer cell lines (1.8-fold in MCF7 and 2.6-fold in MDA-MB-231) compared to normal cell line." (PMID 33333978, 2020). "Consistent with our findings, endogenous expression of SMYD3 was also reported to be significantly up-regulated in a majority of colorectal carcinoma, hepatocellular carcinoma, prostate cancer, and breast cancer specimens." (PMID 32007952, 2020). "In breast cancer cells, SMYD3 was found to tri-methylate the HER2 protein at lysine 175, and this post-translational modification (PTM) stimulates its activation through autophosphorylation." (PMID 31935919, 2020). "Aberrant expression of SMYD3 has been shown to be oncogenic and is essential for the proliferation of most colorectal, hepatocellular, and breast carcinomas, as well as prostate cancer." (PMID 33333978, 2020). "Despite the connection between SMYD3-overexprssion and several types of carcinogenesis, few studies have targeted SMYD3 inhibition in the context of breast cancer through the design of the inhibitors." (PMID 33333978, 2020). "In a comprehensive genomic and transcriptomic analysis of 51 human KMTs in a panel of breast cancer cell lines and primary breast cancer samples, SMYD3 was identified among the eight KMTs with high-level amplification and most clinical relevance." (PMID 31935919, 2020). "In this study, we sought to design small molecule inhibitors for the inhibition of SMYD3-mediated methylation, proliferation, colony formation, and viability in breast cancer cells." (PMID 33333978, 2020). "Another study demonstrated that SMYD3 is essential for estrogen receptor-mediated transcription in breast cancer cells by down-regulating SMYD3 via RNA interference." (PMID 33333978, 2020). "SMYD3 mediated-H2A.Z methylation has also been shown to trigger cyclin A1 gene expression, leading to cell cycle activation in breast cancer cells." (PMID 33333978, 2020). "Recently, SMYD3 was suggested as a potential prognostic biomarker for diagnosis of prostate cancer, breast carcinoma (BrCA) and colorectal cancer (CRC)." (PMID 31935919, 2020). "Reverse-transcription quantitative PCR (RT-qPCR) and Western blotting were used to examine EZH2 and SMYD3 expression in breast cancer tissues and cells." (PMID 29089464, 2018). "The results showed that the mRNA and protein expression of EZH2 and SMYD3 in breast cancer cells MCF-7, MDA-MB-231, T47D, and Bcap-37 were higher than those in normal breast epithelial cells MCF-10A (P<0.05)." (PMID 29089464, 2018). "We also identified that knockdown of SMYD3 attenuated this autophosphorylation in breast cancer cells." (PMID 28639750, 2017). "SMYD3 has been reported to be highly overexpressed in colon cancer, liver cancer, breast cancer, and prostate cancer." (PMID 27042856, 2016). "We previously reported that SMYD3 is overexpressed in colorectal, hepatocellular and breast cancers, and plays a critical role in tumorigenesis." (PMID 27626683, 2016). "SET and MYND domain-containing protein 3 (SMYD3) is a protein lysine methyltransferase, involved in colorectal cancer, hepatocellular carcinoma and breast cancer." (PMID 27626683, 2016). "An oncogenic role of SMYD3 has been suggested in several cancer models, including colorectal, hepatocellular, cervical and breast carcinomas." (PMID 25980436, 2015).
breast carcinoma (continued). "For ASH1L, 11 of 20 cell lines; for SMYD2, 14 of 20; and for SMYD3, 6 of 20 breast cancer cell lines had two-fold higher mRNA levels." (PMID 25537518, 2015). "For instance, knockdown of SMYD3 induced apoptosis through G1-phase cell cycle arrest in breast cancer cell line MDA-MB-231, and MAGI2 cooperates with PTEN to inhibit the growth of tumor cells by suppressing the activation of Akt." (PMID 25889623, 2015). "SMYD3 is overexpressed in a variety of tumor types, including hepatocellular carcinomas and breast cancers, with poor prognosis commonly observed." (PMID 25738358, 2015). "Globally, however, the results reported for SMYD3 silencing in PCa cells are in line with those reported for hepatocellular, colorectal, cervical and breast cancers, which further supports an oncogenic role for SMYD3." (PMID 25980436, 2015). "Several lines of evidence suggest that SMYD3 is frequently overexpressed in human colorectal, liver and breast cancers, and its enhanced expression is considered essential for the growth of certain cancer cells." (PMID 23285160, 2012). "Enhanced expression of SMYD3 has been observed in numerous tumors including colorectal, hepatocellular and breast cancer." (PMID 20525348, 2010). "Similarly, combined administration of trametinib and αPD-1 antibody inhibited SMYD3/SHCBP1-dependent breast cancer progression in xenografts by suppressing MEK activation and promoting CD4/8+ cell infiltration." (PMID 41009347, 2025). "Additionally, the splenomegaly phenotype was reversed, without obvious cytotoxicity in the spleen and liver, demonstrating that Tra has a significant inhibitory effect in mammary tumors with elevated Smyd3-Shcbp1 signaling." (PMID 40157910, 2025). "Further analysis of different types of breast cancer showed that approximately 30% of invasive lobular carcinomas exhibited SMYD3 amplification, and high expression of SMYD3 was also observed in invasive lobular carcinoma and invasive ductal carcinoma in the Curtis and TCGA breast cancer database." (PMID 40157910, 2025). "To test this hypothesis, we used the HP (HP5712) cell line, which was derived from a spontaneous mammary tumor in an FVB female mouse with relatively high protein levels of both Smyd3 and Shcbp1." (PMID 40157910, 2025). "In addition, SMYD3 promotes EMT in breast cancer by directly interacting with SMAD3, but this interaction is not necessary for SMAD2/3 phosphorylation." (PMID 39482529, 2024). "Therefore, our results confirmed that ZNF8 promoted the transcriptional activation of lung metastasis signature genes by recruiting SMYD3 subsequently promoting breast cancer metastasis." (PMID 39225541, 2024). "SMYD3 assumes a crucial role in tumorigenesis, as evidenced by its consistently elevated expression during the initiation and progression of various tumor types, including colorectal cancer, hepatocellular cancer, breast cancer, and ovarian cancer." (PMID 38191478, 2024). "Moreover, our clinical studies suggested that the prognostic significance of SMYD3 in breast cancer is influenced by ZNF8 expression, further highlighting the key role of ZNF8 in this axis." (PMID 39225541, 2024). "In breast cancer, SMYD3 is related to chemoresistance to cisplatin." (PMID 39482529, 2024). "In BRCA, there was a small negative correlation between SMYD4 and SMYD3, which is expected since SMYD3 upregulation is already known to be associated with breast cancer proliferation." (PMID 38892284, 2024). "Furthermore, higher SMYD3 levels are correlated with reduced metastasis-free survival in breast cancer patients." (PMID 39482529, 2024).